PIK3CA (phosphatidylinositol-4,5-bisphosphate 3-kinase catalytic subunit alpha)
Diseases named in the same sentence as PIK3CA in open-access papers (continued):
Sharing a sentence is not in itself a finding about the gene and the disease.
breast cancer (continued). "However, it has not yet been clearly determined whether PIK3CA somatic mutations are also involved in the naturally occurring mammary tumors in other species." (PMID 31842489, 2019). "Therefore, other strategies, such as the inclusion of inhibitors of other signal transduction pathways might improve survival for women with luminal B-like breast cancer subtype in the absence of PIK3CA mutation." (PMID 29707142, 2018). "Evaluation of ERα activation, in addition to PIK3CA mutation status, might be helpful in identifying patients who are likely to benefit from endocrine therapy alone versus those who are not in postmenopausal ER-positive early breast cancer." (PMID 29707142, 2018). "We further analyzed correlation whether a combination of PIK3CA mutation status, AKT phospho-Ser473 (pAKT) and ERα phospho-Ser167 (pER) had any predictive function with regard to clinicopathological characteristics and disease-free survival in postmenopausal ER-positive, HER2-negative breast cancer." (PMID 29707142, 2018). "Finally, the prognostic impact of PIK3CA in breast cancer is not well established, and our data are consistent with the findings in a recent study, reporting no influence of PIK3CA mutation status on survival outcome among 1008 patients with breast cancer at high risk of relapse." (PMID 28213783, 2017). "In contrast, SKBr-3 carries the wild-type of PIK3CA and represents a preclinical model of HER2 gene amplified breast cancer that expresses high levels of EGFR." (PMID 29100381, 2017). "To confirm MiSL's prediction, we treated a panel of PIK3CA mutant (MCF-7, T47D, CAL-148, CAL-51) and PIK3CA wild-type (CAL-120, HCC-1806, HCC-38, SKBR-7) breast cancer cell lines with MK-2206 in 5-day cell viability assays and colony-formation assays." (PMID 28561042, 2017).
breast cancer (continued). "In breast cancer, it was recently shown that PDK1 inhibition was able to re-sensitize PIK3CA-mutant cells to PI3Kα inhibitors through suppression of SGK1 and reduction of mTORC1 activity." (PMID 29064423, 2017). "It exhibits potent anti-proliferative and anti-tumor activities in a variety of cancers including breast cancer, nasopharyngeal carcinoma and lung squamous cell carcinoma (LSCC) in a PIK3CA-dependent manner." (PMID 28592260, 2017). "We constructed a comprehensive discrete dynamic network model of signal transduction in ER+ breast cancer based on the literature of ER+, HER2+, and PIK3CA-mutant breast cancers." (PMID 29623959, 2017). "We assembled a panel of cell lines from our PIK3CA‐H1047R mouse mammary tumors, generated human HS578T‐H1047R and ‐E545K breast cancer cell lines, and obtained cell lines derived from recurrent H1047R mouse tumors (RDR‐C234 and RDR‐A677)." (PMID 28296140, 2017). "In PIK3CA-mutant and HER2+ breast cancer cells, PI3K/AKT signaling frequently drives mTORC1, which in turn activates p70S6 kinase (p70S6K)." (PMID 28423521, 2017). "In breast carcinomas, we observed high similarity between PTEN and PIK3CA, which play complementary roles in regulating cellular proliferation." (PMID 29322935, 2017). "In two patients (4%) BRCA 1, PIK3CA and HER2 alterations, which are commonly found in breast cancer, were observed." (PMID 28050231, 2016). "The oncogenetic tree model was built on CNV of ErbB2, AKT2, KRAS, PIK3CA, PTEN, and CCND1 genes in 963 cases of tumors with sequencing and CNA data of human breast cancer from TCGA." (PMID 27190992, 2016). "In breast cancer models, we found an increased requirement for ERBB3 and PIK3CA, members of the ERBB2 and PI3-kinase signaling pathways that are frequently dysregulated in this cancer histology." (PMID 26947069, 2016). "A variety of genes, including PIK3CA, PTEN, TOP2A and MET are candidate markers for prognosis and response to treatment in ERBB2-positive breast cancer." (PMID 27576528, 2016). "Furthermore, we provide proof-of-principle data utilizing the breast cancer cell line BT474, confirming their dependency on amplification of the epidermal growth factor receptor HER2 and mutation of phosphatidylinositol-4,5-biphosphate 3-kinase (PIK3CA) when grown as tumor spheroids." (PMID 28060271, 2016). "Dysregulation of its components, such as PTEN, PIK3CA, and AKT (PKB), are common in solid tumours but despite evidence for FOXO3a down-regulation in breast cancer, the AMPK-FOXO3a pathway is still inducible." (PMID 25678856, 2015). "miR-148b was reported to reduce breast cancer malignancy by coordinating a novel pathway involving the PI3K catalytic subunit p110α (i.e., PIK3CA)." (PMID 25893379, 2015). "Among the recurrent gene amplifications were oncogenes PIK3CA and MYC, also known to be frequently amplified in breast cancers." (PMID 25970776, 2015). "In addition, PIK3CA mutations were reported to be present in approximately 25 % of breast cancers, particularly the estrogen receptor–positive subtypes, while they are absent in the basal-type breast cancer." (PMID 26148869, 2015).
breast cancer (continued). "However breast cancer cells harboring PIK3CA mutations are selectively sensitive to mTOR allosteric and kinase inhibitors but not in breast cancer cells with loss of PTEN, suggesting that the functional consequences of these two mechanisms of mTOR activation are quite distinct." (PMID 25209360, 2014). "Furthermore, we reveal sets of miRNAs associated with genes frequently amplified (ERBB2) or mutated (p16INK4a, PIK3CA and/or PTEN, E-cadherin, BRCA1) in breast cancer cell lines and thus these miRNAs may contribute to the function of these oncogenes/tumor suppressors." (PMID 23601657, 2013). "Interestingly, no PIK3CA mutations were detected in cfDNA from localized breast cancers (n = 30)." (PMID 23320751, 2013). "Both PIK3CA and PTEN mRNA expression was significantly increased in breast carcinoma tissue compared to normal breast tissue (p = 2 × 10-11) and (p < 0.001), respectively." (PMID 24083111, 2013). "Targeting PIK3CA mutant tumors with a PI3K pathway inhibitor and fulvestrant is therefore a feasible strategy for aromatase-inhibitor-resistant ER-positive relapsed breast cancer." (PMID 21362200, 2011). "For the first time, we have identified somatic mutations in genes related to the AKT/MAPK signaling pathways, such as EGFR, PIK3CA, KRAS, HRAS and NRAS, in brain metastases of breast cancer and other types of cancer." (PMID 20604919, 2010). "To determine whether the mutation of PIK3CA correlated with the activation of Akt (a downstream gene of PIK3 that mediates carcinogenic events such as proliferation), we performed western blot analysis to check the phosphorylation of Akt in several breast cancer cell lines." (PMID 16168105, 2005). "In breast cancer, the PI3K/AKT/mTOR pathway plays an important role in driving cancer progression and is activated by PIK3CA (phosphatidylinositol-4,5-bisphosphate 3-kinase catalytic subunit alpha) mutations, loss of PTEN, or hyperactivity of upstream growth factor signaling." (PMID 40678416, 2025). "According to the RT-qPCR results, the hub genes SRC, PIK3CA, and EGFR may be involved in the anti-breast cancer effects of TSAC." (PMID 40864816, 2025). "The hub targets identified for SRC, PIK3R1, PIK3CA, STAT3, and EGFR may represent significant therapeutic targets for the treatment of breast cancer using TSAC." (PMID 40864816, 2025). "When adjusted for standard of care (ESCAT I‐II) genes (i.e., PIK3CA, ESR1, and ERBB2 for breast cancer; KRAS, NRAS, and BRAF for colon cancer, etc.), 37 (3.6%), 0 (0%), 1 (0.2%), and 0 (0%) of mutant alleles would have been negative among breast, bowel, lung, and skin cancer samples, respectively." (PMID 40056420, 2025).
breast cancer (continued). "For example, alpelisib, as a drug targeting PI3Kα, combined with fulvestrant are used to treat advanced or metastatic postmenopausal female or male breast cancer (whose tumor is HR positive, HER2 negative, and with the PIK3CA mutation)." (PMID 39742381, 2024). "In hormone receptor-positive and HER2-negative breast cancers, a growing number of revolutionary personalized therapies are in clinical use or trials, such as CDK4/6 inhibitors, immune checkpoint inhibitors, and PIK3CA inhibitors." (PMID 39796647, 2024). "PIK3CA and c-MET are often co-altered across various cancer types, including breast cancer." (PMID 39769140, 2024). "Furthermore, LY3484356 has displayed additivity in combination with CDK4/6 inhibitors, mTOR inhibitors, and PIK3CA inhibitors in blocking cell proliferation, as well as tumor growth inhibition in xenograft and PDX models of breast cancer." (PMID 39767607, 2024). "Surprisingly, high CCND1 levels did not predict outcomes in breast cancer patients, irrespective of the PIK3CA status." (PMID 38273040, 2024). "Subsequently, we performed qRT–PCR for verification, and the results showed that after adding GluOC into MDA-MB-231 breast cancer cells, the levels of ROCK1, JAK2, PIK3CA, Bcl-2, CREB were significantly increased, while the expression levels of Bax were significantly decreased." (PMID 39054484, 2024). "One study found that alpelisib exerted a significant anti-tumour effect in PIK3CA mutant canine HSA cell lines but not in PIK3CA mutant canine mammary tumour cell lines." (PMID 38787171, 2024). "In breast cancer, PD-1/PD-L1 may affect various signaling pathways, such as PTEN/PIK3CA, ERBB2 and STAT3, affecting various biological processes of tumor cells and the interaction between tumor cells and immune cells." (PMID 37154982, 2023). "Indeed, we and others have shown that sensitivity to AKT inhibitors was observed in both PIK3CA-mutant/PTEN-wild-type and PIK3CA-wild-type/PTEN-null breast cancer cell lines, and sensitivity to AKT inhibitors correlated with SGK and p-AKT expression levels." (PMID 36901954, 2023). "Therefore, in this study, we established new CMT cell lines by isolating cells from tumor tissues and investigated phosphatidylinositol-4,5-bisphosphate 3-kinase catalytic subunit alpha (PIK3CA), a target for human breast cancer." (PMID 38033642, 2023). "The dependency evaluation of the cell lines with SCRIB, VANGL2 and NOS1AP amplifications with CRISPR and RNAi revealed several genes involved in breast cancer pathogenesis, such as FOXA1, ERBB2, PIK3CA and CDK4, to be among the top preferential essential genes." (PMID 36675340, 2023). "Likewise, the AKT inhibitor drug AZD5363 in patients with AKT1 E17K-mutant ER+ breast cancer and MK-2206 in patients with PIK3CA-mutant ER+ and HER2– breast cancer was investigated in neoadjuvant settings for individualized treatment options." (PMID 37190133, 2023). "At the time of enrollment, PIK3CA inhibitors were not the standard of care for patients with breast cancer." (PMID 36832270, 2023). "In breast cancer, the main biomarkers (endocrine receptors, HER2, PD-L1, BRCA, PIK3CA..)." (PMID 37176102, 2023). "PIK3CA inhibitors, such as alpelisib, are being developed for treating specific subgroups of human breast cancer, such as HER2 negative, PIK3CA mutation positive advanced stage breast cancer." (PMID 36635367, 2023). "BYL-719 is currently approved for some cases of PIK3CA mutated ER+ breast cancer, though such as with HCI-011, targeting PIK3CA in ER+ disease, even with pathogenic PIK3CA, does not always yield an effective treatment." (PMID 36900375, 2023).
breast cancer (continued). "For the PIK3CA gene, somatic copy number alterations in pre-treatment tumour biopsies included copy number gain in ~45% (10/22) or amplification in ~18% (4/22) of HER2+ breast cancer cases." (PMID 37758711, 2023). "The preclinical data presented here suggest that a trial relying on PIK3CA inhibition to target DTCs and prevent breast cancer metastasis would not meet the surrogate endpoint of DTC clearance or the functional endpoint of enhanced MFS." (PMID 34058066, 2022). "Since initiation of this trial, three PIK3CA inhibitors have been approved by the FDA including, copanlisib (for refractory lymphoma); duvelisib (for refractory CLL and follicular B-cell lymphoma); and alpelisib (for refractory breast cancer)." (PMID 36330484, 2022). "In contrast, among patients with any type of breast cancer, PIK3CA was found to be a negative prognostic factor for survival outcomes comparing mutated vs wild-type PIK3CA patients in clinical trials." (PMID 36131248, 2022). "Namely, it is an eQTL (expression quantitative trait locus) for PIK3CA (P = 0.011) in tumors from METABRIC14, is located at its promotor region and at a DNAse I hypersensitivity site, and is bound by POL2 in a breast cancer cell line." (PMID 35676284, 2022). "Paradoxically, despite worse outcomes for patients with HR+PIK3CA-mutant breast cancer, patients with PIK3CA-mutant TNBC tend to have higher rates of overall survival compared with patients with subtype-matched tumors that express wild-type PIK3CA." (PMID 36381235, 2022). "In contrast, knockdown of p85β had no impact on cell proliferation and colony formation of PIK3CA H1047R mutant T47D breast cancer cells and PIK3CA WT SW480 colon cancer cells." (PMID 35418124, 2022). "Alpelisib is a drug used to treat breast cancer that has certain characteristics (hormone receptor-positive (HR+), human epidermal growth receptor 2-negative (HER2–), PIK3CA-mutated) and that has or has not spread to other organs." (PMID 35406370, 2022). "Although initial results with these new inhibitors showed partial responses of about 6% in patients with PIK3CA (mutant) breast cancer, no responses had been detected in patients with PIK3CAI (wild-type) tumors." (PMID 35495618, 2022). "The analysis of a prospectively collected and unselected cohort of non-metastatic breast cancer patients with a huge sample size is the strength of our PIK3CA study." (PMID 36279023, 2022). "Here, we track the transitions and heritability of metabolic states in single PIK3CA mutant breast cancer cells, identify non-genetic glycolytic heterogeneity, and build on observations derived from methods reliant on bulk analyses." (PMID 33596424, 2021). "Taken together, these data show that the technology of liquid biopsy for ctDNA analysis has been successfully used in patients with breast cancer to identify PIK3CA alterations without additional invasive testing." (PMID 33842357, 2021). "PIK3CA (5290) and PPM1D (8493) are two breast cancer gene markers in the GSE1561 dataset." (PMID 34573857, 2021).